ALDOA (aldolase, fructose-bisphosphate A)
Diseases named in the same sentence as ALDOA in open-access papers (continued):
Sharing a sentence is not in itself a finding about the gene and the disease.
tumor (continued). "This suggests a dual role for ALDOA: driving tumor cell intrinsic glycolysis, and simultaneously functioning within the TAM population." (PMID 41239433, 2025). "It directly targets the tyrosine sites in ALDOA, effectively blocking metabolism in both primary and metastatic tumor cells and inhibiting the expression of specific genes in tumor cells." (PMID 40887473, 2025). "In clinical tissue samples, PTMs were quantitatively assessed, highlighting the pivotal role of ALDOA K330 ubiquitination/acetylation in tumor progression." (PMID 40777122, 2025). "Incubation of ESCC cells harboring ALDOA Y174A, Y302A, or Y328A with G3P (1 μM) rescued the expression of these tumor-promoting molecules in primary ESCC cells." (PMID 40887473, 2025). "In an IHC analysis of NSCLC tumour samples, higher ALDOA levels correlate with increased metastatic potential and reduced survival rates." (PMID 41154605, 2025). "ALDOA overexpression in LUSC was significantly correlated with advanced tumor stage, disease progression, and poor overall survival." (PMID 41239433, 2025). "In CRC, ALDOA acts as a critical regulator of fructose metabolism, facilitating tumor progression through enhanced glycolysis and cellular proliferation, with its high expression linked to therapy resistance and poor prognosis." (PMID 40520908, 2025). "In this study, we observed an elevated expression of ALDOA in human CRC tissues and a positive correlation of elevated ALDOA expression with tumor size, invasion depth, LNM, and TNM stage." (PMID 39755705, 2025). "The TIMER results confirmed that in GC, ALDOA is associated with B cells, CD4+ T cells, and macrophages in the infiltrating tumor tissues (P < 0.001)." (PMID 41049005, 2025). "This suggests a potential role for ALDOA in shaping the tumor immune microenvironment (TIME) by influencing macrophage infiltration and polarization." (PMID 41239433, 2025). "Consistent with the in vitro data, xenografts with stable ALDOA knockdown grew at a slower rate and had a significantly lower tumor weight than the control group (P < 0.01)." (PMID 39755705, 2025). "The dual role of ALDOA in tumor cell-intrinsic metabolism and the immune microenvironment provides a strong rationale for several targeted approaches." (PMID 41239433, 2025). "Both Aldoa shRNAs (shAldoa.1280 and shAldoa.558) strongly reduced tumour development and prolonged survival of tumour-bearing animals in comparison to a nontargeting control shRNA (shRen), indicating that ALDOA is essential for liver tumour development." (PMID 39833612, 2025). "We discovered that ALDOA is not only highly expressed in tumor cells but is also remarkably enriched in CD68 + macrophages themselves." (PMID 41239433, 2025). "Considering the heterogeneity of HCC patients, subgroup analysis was performed based on tumor-node-metastasis (TNM) stage and demonstrated that ALDOA overexpression was consistently associated with poor survival regardless of TNM stage." (PMID 40708574, 2025). "In contrast, ALDOA-low tumors were enriched in the C2 (IFN-γ-dominant) subtype, which is typically associated with enhanced anti-tumor immunity." (PMID 41239433, 2025). "For instance, ALDOA promotes tumor cell migration and invasion by binding to actin (F-actin) and playing a role in cell membrane ruffling and motility." (PMID 41153403, 2025). "In CRC, relative to healthy glandular epithelium tissues, ALDOA was found to be substantially expressed in tumor tissues and liver metastatic CRC, and an elevated level of ALDOA contributed to the poor survival outcomes in CRC patients." (PMID 39755705, 2025). "ALDOA enhances the glycolytic capacity and invasiveness of cancer cells, thereby promoting tumor progression." (PMID 40520908, 2025). "Immunohistochemical staining analysis confirmed that ALDOA protein levels were upregulated in 104 paired liver tumor specimens and the intensity of ALDOA in the nuclei of tumor tissues dramatically increased." (PMID 40708574, 2025).
tumor (continued). "Given its multifaceted role in metabolic regulation, tumor progression, and immune suppression, ALDOA represents an attractive therapeutic target for LUSC." (PMID 41239433, 2025). "To further explore the role of ALDOA in the tumor immune microenvironment (TIME) of LUSC, we conducted a series of immune infiltration and immune checkpoint analyses." (PMID 41239433, 2025). "Functional enrichment and drug sensitivity analyses were conducted to explore ALDOA’s role in tumor progression and therapeutic resistance." (PMID 41239433, 2025). "Regarding tumor mutational burden (TMB), ALDOA expression showed a positive correlation in UCEC (p < 0.01) and STAD (p < 0.05) but a negative correlation in SARC (p < 0.01) and LAML (p < 0.05)." (PMID 41239433, 2025). "ALDOA expression was significantly elevated in LUSC tumor tissues compared to normal tissues at both mRNA and protein levels (p < 0.001)." (PMID 41239433, 2025). "We carried out a cluster analysis based on the expression of ALDOA/ENO1 in tumor and normal tissues." (PMID 41049005, 2025). "It is plausible that ALDOA-mediated glycolysis is essential for the metabolic fitness, survival, and pro-tumor functions of TAMs within the hypoxic TME." (PMID 41239433, 2025). "The tumor-promoting role of ALDOA in HCC was confirmed through both in vitro and in vivo experiments." (PMID 40708574, 2025). "Furthermore, these models could be used to investigate the potential molecular mediators, such as secreted cytokines or metabolic by-products (e.g., lactate), through which ALDOA-overexpressing tumor cells communicate with and reprogram tumor-associated macrophages." (PMID 41239433, 2025). "Consistent with public data, IHC staining demonstrated an enhanced amount of ALDOA at the protein level in CRC tumor tissue samples (P < 0.01)." (PMID 39755705, 2025). "Further analysis showed that ALDOA protein levels in CRC tumor tissues with deeper invasion (T3-4) and positive lymph node metastasis (LNM) were significantly higher compared with tissues with T1-2 and negative LNM, respectively." (PMID 39755705, 2025). "In this study, we examined alterations in ALDOA expression and their effect on clinical survival by integrating bioinformatics analysis with the examination of tumor tissues." (PMID 41049005, 2025). "As a pivotal glycolytic enzyme, high ALDOA expression inevitably accelerates glycolytic flux in tumor cells, leading to massive lactate production and secretion." (PMID 41239433, 2025). "For instance, polysaccharides have been shown to target metabolic enzymes such as an α-D-glucan binding to ALDOA or other functional proteins such as safflower polysaccharide HH-1 targeting galectin-3 to inhibit tumor growth." (PMID 41451369, 2025). "Second, beyond its cell-autonomous role in tumor cell metabolism, our single-cell and spatial transcriptomic analyses unveil a more direct and intriguing connection between ALDOA and macrophages." (PMID 41239433, 2025). "Through the Oncosplicing database, we identified 130 ALDOA alternative splicing events, including ALDOA_RI_36050, which exhibited significant tumor-specific splicing pattern." (PMID 41239433, 2025). "These experiments would determine if tumor-intrinsic ALDOA expression directly drives macrophage recruitment and polarizes them toward an immunosuppressive M2-like phenotype." (PMID 41239433, 2025). "Remarkably, ALDOA emerges as an extracellular protein contributing to the suppression of tumor progression." (PMID 38389836, 2024). "Compared with the control group, the sh-ZNF692 and sh-ALDOA groups showed lower tumor growth rates (P < 0.05)." (PMID 38453820, 2024). "The results indicated that the expression levels of ALDOA and p-AKT in tumor tissues were remarkably higher than those in normal tissues, and the expression levels of ALDOA and p-AKT were correlated to a certain extent." (PMID 38499636, 2024). "Acetylation seems to be an important modification that modulates ALDOA expression and activity in tumor cells." (PMID 38453820, 2024).
tumor (continued). "The large‐scale multi‐omics analysis of liver tissues revealed that ALDOA is elevated in HCC samples and this elevation is associated with the tumor progression and poorer patient overall survival." (PMID 39099416, 2024). "The aberrant expression of ALDOA in various tumor cells promotes the EMT process of tumor cells, enhances proliferation, and accelerates the transition from G1 to G2 phase of cell cycle by regulating tumor metabolism." (PMID 38499636, 2024). "After investigating the association of ALDOA and p-AKT expression in tumor tissue, we also assess the association in normal tissue." (PMID 38499636, 2024). "The unique interplay of proteins like PCOLCE, H4, PPIB, and ALDOA within LIV-treated MSC CM underscores their tumor-suppressive attributes." (PMID 38389836, 2024). "Of particular intrigue, a peptide fragment of ALDOA denoted as P04 (IGEHTPSALAIMENANVLAR) exhibits anti-tumor properties, akin to another antitumor peptide." (PMID 38389836, 2024). "Given that ALDOA was identified as one of the tumor-suppressing proteins in MSC CM, we sought to extend this analysis to evaluate the role of an ALDOA-derived peptide, P04 (IGEHTPSALAIMENANVLAR)." (PMID 38389836, 2024). "Studies indicates that ALDOA expression is elevated in a variety of tumor tissues, but the alteration of its expression in CRC tissue and adjacent normal tissue, and its potential influence have not been fully investigated." (PMID 38499636, 2024). "The analysis of the TCGA database revealed that ALDOA exhibits high expression in various tumor tissues, including HCC." (PMID 39099416, 2024). "Subsequently, we calculated the difference of IHC score of ALDOA between CRC and paired normal tissues, and analyzed the expression of ALDOA in tumor tissue and matched normal tissue was analyzed." (PMID 38499636, 2024). "The results showed that ALDOA K230/322R‐treated LCSCs generated significantly lower tumor volume and weight compared to the ALDOA WT group." (PMID 39099416, 2024). "ALDOA is a pivotal enzyme in the glycolytic pathway, and its knockdown can inhibit tumor growth and migration under hypoxia." (PMID 39625960, 2024). "The progression of tumor is accompanied by metabolic reprogramming, and ALDOA acts as an important role in tumor metabolism." (PMID 38499636, 2024). "Upon knockdown of the metabolic-related genes, direct tumor cell killing was observed for most cell lines and target genes when cultured with T-cells, especially for ALDOA in both luminal and basal-like cells, and TPI1 in luminal cells." (PMID 38714665, 2024). "It suggested that if the expression of ALDOA in tumor tissue is used to predict the prognosis of CRC patients, the prediction is more accurate for early CRC patients." (PMID 38499636, 2024). "According to previous studies, and considering the potential role of ALDOA expression in the process of gluconeogenesis and glycolysis of tumor cells, we explored the potential correlation between ALDOA and AKT, another important upstream target of mTOR20–22." (PMID 38499636, 2024). "LIV not only upregulated ALDOA expression in PBMCs but also endowed their CM with potent tumor-suppressing properties." (PMID 37896207, 2023). "Intriguingly, the CM derived from ALDOA-overexpressing MSCs demonstrated a profound tumor-suppressive effect by curtailing the viability, proliferation, motility, and invasion of PANC1 cells, along with PANC198 cells." (PMID 37896207, 2023). "Tumor tissues from HCC patients were probed with anti-ALDOA, anti-CD68, anti-CD163, anti-CD4 and anti-FOXP3 antibodies." (PMID 36937389, 2023). "The result showed that ALDOA overexpression partially rescued the inhibitory effect of PSMA3-AS1 knockdown on tumor volume and weight in nude mice." (PMID 37403106, 2023). "MiR-329-3p knockdown or ALDOA overexpression partially reversed the tumor-suppressive effect of PSMA3-AS1 knockdown." (PMID 37403106, 2023).
tumor (continued). "In contrast, ALDOA overexpression strongly accelerated tumor growth, accompanied by higher Ki67 staining." (PMID 37431681, 2023). "Our previous investigations underscored that the anti-tumor efficacy of ALDOA is facilitated by its interaction with EGFR." (PMID 37896207, 2023). "Aldolase A (ALDOA) is an enzyme that plays an important role in glycolysis and gluconeogenesis, which is closely related to tumor metabolism." (PMID 35804089, 2022). "The expression of ALDOA in tumor tissues was examined by WB, which showed that ALDOA remained stably knockdown in nude mice." (PMID 36494481, 2022). "Among aldolases, ALDOA as a glycolytic and gluconeogenic enzyme receives its prospective attention as a hypoxia-inducible tumor prognostic factor." (PMID 36077431, 2022). "As far as we know, this is the first report on the correlation between ALDOA and tumor immune infiltration." (PMID 35804089, 2022). "Through this in vivo experiment, we observed that stable knockdown of ALDOA effectively inhibited tumour growth in nude mouse." (PMID 36494481, 2022). "Further studies can be performed to elucidate functions and detailed molecular mechanisms of ALDOA in tumor metabolism and immune microenvironment." (PMID 35804089, 2022). "Knockdown of PINK1-AS expression will result in down-regulation of ALDOA levels, and inhibited the aerobic glycolysis process of tumor cells." (PMID 36494481, 2022). "Bioinformatics analysis shows that the expression of PINK1-AS and ALDOA is positively correlated in tumor samples." (PMID 36494481, 2022). "Increasing ALDOA expression accelerates the process of glycolysis in tumour cells, while decreasing ALDOA expression decreases ATP production and reduces cell membrane integrity." (PMID 36494481, 2022). "Aldolase A (ALDOA), an important metabolic enzyme in the glycolytic pathway, plays an important role in regulating tumour metabolism." (PMID 36494481, 2022). "IHC was used to detect the distribution of ALDOA in tumour and paraneoplastic tissues, and it was found that ALDOA was mainly expressed in HCC tissues and to a lesser extent in paraneoplastic tissues." (PMID 36494481, 2022). "We further evaluated the correlation between the expression of ALDOA and tumor immune cell infiltration in pan-cancer." (PMID 35804089, 2022). "We found that the pathways in which ALDOA was closely involved were tumor metabolism and smooth muscle contraction." (PMID 34099027, 2021). "To further confirm the relationship between ALDOA expression and tumor progression, we overexpressed ALDOA in low-ALDOA-expressing FRH-0201 cell line and high-ALDOA-expressing HuCCT1 cell line by plasmid respectively." (PMID 33994862, 2021). "Knocking down the expression level of ALDOA or blocking its enzyme activity can significantly inhibit tumor progression." (PMID 33994862, 2021). "CCK-8 test illustrated that the knockdown of ALDOA significantly inhibited the proliferation of tumor cell lines." (PMID 33994862, 2021). "After adjusting the correlation by tumor purity, these results revealed that there was a correlation between ALDOA expression and most immune marker sets." (PMID 34925439, 2021). "What’s more, the nude mice which were intracranially transplanted with the ARST/ALDOA double upregulated cells exhibited larger tumor size and poorer prognosis compared to that transplanted with oeARST cells." (PMID 34099027, 2021). "By using an inhibitor (Itaconate) to repress the enzymatic activity of ALDOA, we found that the tumor proliferation and invasion were suppressed, suggesting that ALDOA promotes ICC cell proliferation through its enzymatic activity." (PMID 33994862, 2021). "Since the knockdown of ALDOA significantly inhibited proliferation and invasion of ICC tumor cell lines in vitro, we further examine the role of ALDOA in tumor cell proliferation and tumorigenesis in vivo." (PMID 33994862, 2021).
tumor (continued). "Based on both gluconeogenesis and glycolysis can provide energy for tumor proliferation, accumulating evidence has indicated that ALDOA plays an important role in the pathological progress of several cancers." (PMID 34925439, 2021). "A stable ALDOA knockdown RBE tumor cell line was constructed with lentiviruses and a nude mouse subcutaneous xenograft model was established with this ALDOA-konckdown RBE cell line." (PMID 33994862, 2021). "In the previous study, we analyzed GEO, TCGA and other databases for tumor metabolic genes and found that the expression level of glycolytic enzyme ALDOA in liver tumors, especially in ICC, was significantly increased." (PMID 33994862, 2021). "Seahorse Glycolysis Stress test showed that ALDOA knockdown significantly inhibited the glycolysis level of tumor cells but barely affected the mitochondrial metabolism according to the Cell Mito Stress test." (PMID 33994862, 2021). "In the research of other solid tumors, some researchers pointed out that ALDOA mainly participates in the regulation of tumor development by involving in the regulation of cell signal transduction pathways, such as c-MYC/HIF-1 pathway 42, 43 or EMT pathway." (PMID 33994862, 2021). "The left shift of the tumor sample mean score represents an increased proximal PAS usage signifying the expected shortening of the ALDOA 3′ UTR." (PMID 32029502, 2020). "The ALDOA protein level significantly correlated with a larger tumor diameter (P = .004), advanced T stage (P < .001), N stage (P < .001) and lymphovascular invasion (P = .001)." (PMID 29992789, 2018). "When silencing the expression of ALDOA, the anaerobic glycolysis was inhibited, ATP levels were reduced, the feed‐forward loop was broken and tumour proliferation and metastases were inhibited." (PMID 29992789, 2018). "Its involvement in tumor metabolism, immune evasion, and therapy resistance suggests that targeting ALDOA could enhance both metabolic inhibition strategies and immune checkpoint blockade therapies." (PMID 41239433, 2025). "An ALDOA inhibitor effectively suppressed the resistant tumor cells." (PMID 40520908, 2025). "Our Tumor Immune Dysfunction and Exclusion analysis showed that ALDOA-high tumors exhibit higher immune exclusion scores, suggesting that patients with elevated ALDOA expression may be less responsive to immune checkpoint blockade therapy." (PMID 41239433, 2025). "The univariate analysis revealed that several factors, including the degree of tumor differentiation, vascular and neural invasion, depth of tumor infiltration, lymph node metastasis, as well as the expression levels of ALDOA and ENO1, significantly influenced patient survival (P < 0.05)." (PMID 41049005, 2025). "The absence of functional experiments, such as ALDOA knockdown or knockout in LUSC cell lines coupled with macrophage co-culture systems, precludes a definitive conclusion that tumor-intrinsic ALDOA directly orchestrates macrophage recruitment and polarization." (PMID 41239433, 2025). "Notably, the downregulation of ALDOA in tumor tissues highlights the metabolic reprogramming that occurs in cancer stem cells, potentially reflecting their unique metabolic dependencies compared to bulk tumor cells." (PMID 40766320, 2025). "Instead, ALDOA may serve as a biomarker for a specific subset of immune-excluded tumors that, upon successful reversal of exclusion, can mount a potent anti-tumor response." (PMID 41239433, 2025). "These in vivo findings further support the potential of ALDOA as a predictive biomarker for immunotherapy response in LUSC, and indicate that its upregulation may reflect a more immunogenic tumor microenvironment susceptible to checkpoint blockade." (PMID 41239433, 2025). "Additionally, proteins associated with neoplasm invasiveness and metastasis (SRC, ALDOA, ACTB, MAPK1, and RAC1) and those mediating epithelial to mesenchymal transition (annexin A1, Hsp27) were upregulated in the LNM group." (PMID 41193833, 2025).